DHRS3 (dehydrogenase/reductase 3)
Description:
Catalyzes the reduction of all-trans-retinal to all-trans-retinol in the presence of NADPH.
Synonyms: retSDR1; RDH17; SDR16C1; Rsdr1; SDR1; CNALPTC1; CRSS; DD83.1
Tractability: Antibody: UniProt predicts a signal peptide or a membrane-spanning region. PROTAC: ubiquitination databases record sites on it; its protein half-life has been measured.
Gene: Protein-coding gene on chromosome 1 (12,567,909 to 12,620,133, reverse strand). Ensembl gene ENSG00000162496.
Subcellular location: Membrane
Subcellular location (Human Protein Atlas): Mitochondria; Nucleoli
Pathways (Reactome):
Sensory Perception: The retinoid cycle in cones (daylight vision)
Signal Transduction: RA biosynthesis pathway
Gene Ontology:
Molecular function: all-trans-retinol dehydrogenase (NADP+) activity; all-trans-retinol dehydrogenase (NAD+) activity; electron transfer activity; nucleotide binding
Biological process: retinoic acid biosynthetic process; regulation of retinoic acid receptor signaling pathway; retinoid metabolic process; retinol metabolic process; visual perception
Cellular component: endoplasmic reticulum membrane; lipid droplet; photoreceptor outer segment membrane; membrane
Genetic constraint (gnomAD): Loss-of-function variants: 14 observed, 27.71 expected, observed/expected ratio (o/e) 0.51, 90% interval 0.33 to 0.79. The upper end of that interval is the gene's LOEUF score, 0.79, which puts it in group 3 of 6, group 1 being the genes least tolerant of losing a copy. Missense variants: 322 observed, 425.27 expected, observed/expected ratio (o/e) 0.76, 90% interval 0.69 to 0.83. Synonymous variants: 165 observed, 185.86 expected, observed/expected ratio (o/e) 0.89, 90% interval 0.78 to 1.01.
Homologues: Orthologues: chimpanzee DHRS3 (100% identical), macaque DHRS3 (99% identical), dog DHRS3 (98% identical), guinea pig DHRS3 (98% identical), rat Dhrs3 (95% identical), mouse Dhrs3 (95% identical), tropical clawed frog dhrs3 (84% identical), zebrafish dhrs3b (79% identical), zebrafish dhrs3a (77% identical), pig DHRS3 (75% identical). Paralogues in human: RDH10 (37% identical), SDR16C5 (35% identical), HSD17B11 (34% identical), HSD17B13 (32% identical), RDH16 (24% identical), HSD17B6 (24% identical), RDH5 (23% identical), HSD17B4 (22% identical), SDR9C7 (21% identical), DHRS9 (21% identical), HSD11B2 (21% identical), HSD17B12 (20% identical), and 13 more.